SNORD63 (Small nucleolar RNA SNORD63 )
Gene: Small nucleolar RNA gene on chromosome 17 (30,246,757 to 30,246,820, reverse strand). Ensembl gene ENSG00000252112.
Homologues: Orthologues: chimpanzee SNORD63 (100% identical), pig SNORD63 (72% identical), dog SNORD63 (69% identical), rat LOC120098354 (67% identical), mouse Gm26109 (62% identical). Paralogues in human: SNORD63 (69% identical), SNORD63B (56% identical), SNORD63 (47% identical).
Diseases named in the same sentence as SNORD63 in open-access papers:
SNORD63 is named in the same sentence as 5 diseases in open-access papers, as found by Europe PMC text mining. Sharing a sentence is not in itself a finding about the gene and the disease. The quoted sentences say what the papers report.
myelodysplastic syndrome (1 paper, 2017). A clonal hematopoietic disorder characterized by dysplasia and ineffective hematopoiesis in one or more of the hematopoietic cell lines. "U60 has been reported as an attenuator of pulmonary vasoconstriction in rats and as a key factor in the regulation of plasma membrane cholesterol, while U63 (SNORD63) is located in a chromosomic region frequently deleted in myelodysplastic syndromes." (PMID 28817650, 2017).
tumor (1 paper, 2022). "We identified 42 DEs and established 6 survival-related snoRNAs using Cox analysis: 2 of the 6 snoRNAs, SNORA16B and SNORD63, are protective factors, and the other 4 (SNORA59B, SNORD11, SNORD46, and SNORD 124) are risk factors that may play a crucial role in tumor metastasis and progression." (PMID 36181013, 2022).
SNORD63 also shares sentences with these, for which no sentence is quoted: clear cell renal cell carcinoma (1 paper); renal carcinoma (1); sarcoma (1).